DVL2 (dishevelled segment polarity protein 2)
Diseases named in the same sentence as DVL2 in open-access papers (continued):
Sharing a sentence is not in itself a finding about the gene and the disease.
tumor (continued). "Considering that the mode of cell death influences the anti-tumor immune response and since DVL2 affects cell growth, further investigation is required to determine the mechanism by which shDVL2 enhances Neratinib in mediating cell death and its influence on the immunogenicity." (PMID 36809986, 2023). "DVL2 was also upregulated in all tumour grades in comparison to control samples." (PMID 30468298, 2019). "Our study explored DVL1, DVL2 and DVL3 gene alterations in association with tumour grade." (PMID 30468298, 2019). "It is derived from several exons of the E3 ubiquitin protein ligase, ITCH, which is known for its tumor suppressive effects via its role in promoting ubiquitin-mediated degradation of DVL2 (dishevelled segment polarity protein 2) to inhibit canonical Wnt signaling." (PMID 29702599, 2018). "We therefore hypothesized that DDX3 could promote tumor malignancy by increasing the stability of the β-catenin protein and by promoting its translocation to the nucleus via the CK1ε/Dvl2 axis." (PMID 26892600, 2016). "Therefore, we hypothesized that DDX3 might promote tumor invasion via the CK1ε/Dvl2 axis due to β-catenin/TCF activation." (PMID 26892600, 2016). "An FDA-approved antiparasitic drug Niclosamide, suppresses tumor growth and metastasis by targeting FZD1, DVL2, and LRP6 with minimal animal toxicity." (PMID 41516083, 2025). "The elevated expression of DVL proteins, particularly DVL2 and DVL3, suggests their major involvement in the development of the tumor." (PMID 39594618, 2024). "The application of this compound hindered tumor development and decreased the production of phosphorylated LPR6, phosphorylate and unphosphorylated DVL2, Ser9 phosphorylated GSK3β, active β-catenin, and cyclin D1." (PMID 35509712, 2022). "Consistent with this, nedd4L has been reported as a tumor suppressor by regulating several protein targets, such as LGR5 and DVL2." (PMID 34769140, 2021). "In conclusion, our work shows that NEDD4 and NEDD4L are crypt‐expressing tumour suppressors by targeting the RSPO receptor LGR5 and DVL2 for degradation." (PMID 31867777, 2020). "In vivo, the ectopic tumor volume and weight were significantly reduced in LV-AQP9 group compared with the control, and the levels of DVL2, GSK-3β, CyclinD1 and β-catenin were down-regulated in tumor tissues." (PMID 31969493, 2020). "For DVL2 gene analysis marker D17S960 was selected and it showed a lower rate of MSI in all tumour grades, 7.1% in grade I, 15.4% in grade II, 0% in grade III and 8.6% in grade VI." (PMID 30468298, 2019). "Hence, in our study we reported a novel role of DVL2 in oncogenic Wnt and EGFR signaling modulation as well as its promising correlation with markers of tumor immune regulation (such as TILs and cytotoxic CD8α)." (PMID 36809986, 2023). "In our study, overexpressed AQP9 reduced the levels of DVL2, p-GSK-3β, CyclinD1 and β-catenin, suggesting that AQP9 could be a novel tumor suppressor by suppressing Wnt/β-catenin signaling pathway." (PMID 31969493, 2020). "Additionally, in tumor tissues collected from A549 xenograft model, ART and its derivatives effectively reduced Wnt5-a/b, LRP6, and Dvl2 but significantly increased both NKD2 and Axin2 (p < 0.001)." (PMID 27119499, 2016).
infection (3 papers, 2010 to 2021). The state of being infected such as from the introduction of a foreign agent such as serum, vaccine, antigenic substance or organism. "According to this, we found reduced levels of pLRP6 in NCI-N87 cells deficient for Dvl2 and Dvl3 after infection with H. pylori." (PMID 20137080, 2010). "To study whether nuclear translocation of β-catenin in H. pylori-infected epithelial NCI-N87 cells depends on LRP6, Dvl2 or Dvl3, we performed an infection of stable knockdown cell lines deficient for LRP6, Dvl2 or Dvl3." (PMID 20137080, 2010). "At 24 h post-infection of small interfering RNA (siRNA)-transfected cells, E. chaffeensis infection level was significantly reduced in nearly all transfection groups, excluding Dvl2 knockdown, relative to the infection level in scrambled siRNA-transfected cells." (PMID 33883266, 2021). "We transferred lentivirus-Dvl2 into primary human RA-FLSs and observed GFP fluorescence using fluorescence microscopy to determine the infection efficiency." (PMID 28187436, 2017). "Loss of intracellular signal relay protein Dvl1 significantly reduced infection, while Dvl2 knockdown did not, suggesting redundant mechanisms are at play at this level of the signaling cascade." (PMID 33883266, 2021).
myopathy (1 paper, 2023). A disease of the muscle in which the muscle fibers do not function properly. "Furthermore, RNA-seq data showed alterations in several genes involved in Wnt signaling, such as APC, DACT1, DKK2, DVL2, and WNT4, emphasizing an important role for Wnt signaling in WB myopathy." (PMID 38130476, 2023).
DVL2 also shares sentences with these, for which no sentence is quoted: anaplastic astrocytoma (1 paper); aortic stenosis (1); Arthritis (1); cholangiocarcinoma (1); colitis (1); ductal carcinoma (1); embryonic carcinoma (1); epilepsy (1); episodic ataxia (1); esophageal squamous cell carcinoma (1); kidney diseases (1); liver fibrosis (1); malignant glioma (1); malignant pleural mesothelioma (1); melanoma (1); neurological diseases (1); non-small cell lung carcinoma (1); orofacial cleft (1); osteoarthritis (1); osteogenesis imperfecta (1); papillary renal cell carcinoma (1); psychiatric disorder (1); renal cell carcinoma (1); retinopathies (1); scoliosis (1); spina bifida (1); squamous carcinomas (1).